GNG3 (G protein subunit gamma 3)
Description:
Guanine nucleotide-binding proteins (G proteins) are involved as a modulator or transducer in various transmembrane signaling systems. The beta and gamma chains are required for the GTPase activity, for replacement of GDP by GTP, and for G protein-effector interaction.
Synonyms: HG3D
Tractability: Antibody: UniProt places it where antibodies can reach, with high confidence; its Gene Ontology location is reachable by antibodies, with high confidence. PROTAC: its protein half-life has been measured.
Gene: Protein-coding gene on chromosome 11 (62,706,400 to 62,712,083, forward strand). Ensembl gene ENSG00000162188.
Subcellular location: Cell membrane
Pathways (Reactome):
Signal Transduction: Ca2+ pathway; Extra-nuclear estrogen signaling; G alpha (12/13) signalling events; G alpha (i) signalling events; G alpha (q) signalling events; G alpha (s) signalling events; G alpha (z) signalling events; G beta:gamma signalling through BTK; G beta:gamma signalling through CDC42; G beta:gamma signalling through PI3Kgamma; G beta:gamma signalling through PLC beta; G-protein activation; GPER1 signaling; Glucagon-type ligand receptors
Hemostasis: ADP signalling through P2Y purinoceptor 1; ADP signalling through P2Y purinoceptor 12; Prostacyclin signalling through prostacyclin receptor; Thrombin signalling through proteinase activated receptors (PARs); Thromboxane signalling through TP receptor
Metabolism: Adrenaline,noradrenaline inhibits insulin secretion; Glucagon signaling in metabolic regulation; Glucagon-like Peptide-1 (GLP1) regulates insulin secretion
Neuronal System: Activation of G protein gated Potassium channels; Inhibition of voltage gated Ca2+ channels via Gbeta/gamma subunits; Presynaptic function of Kainate receptors
Cellular responses to stimuli: High laminar flow shear stress activates signaling by PIEZO1 and PECAM1:CDH5:KDR in endothelial cells
Disease: ADORA2B mediated anti-inflammatory cytokines production
Metabolism of proteins: Cooperation of PDCL (PhLP1) and TRiC/CCT in G-protein beta folding
Transport of small molecules: Vasopressin regulates renal water homeostasis via Aquaporins
Gene Ontology:
Molecular function: protein binding; G-protein beta-subunit binding; GTPase activity
Biological process: G protein-coupled receptor signaling pathway; positive regulation of cytosolic calcium ion concentration
Cellular component: heterotrimeric G-protein complex; plasma membrane; cell body; dendrite; postsynaptic density; synapse
Genetic constraint (gnomAD): Loss-of-function variants: 2 observed, 4.03 expected, observed/expected ratio (o/e) 0.5, 90% interval 0.2 to 1.49. That is too few expected variants to judge how well the gene tolerates losing a copy. Missense variants: 44 observed, 85.16 expected, observed/expected ratio (o/e) 0.52, 90% interval 0.41 to 0.66. Synonymous variants: 23 observed, 29.11 expected, observed/expected ratio (o/e) 0.79, 90% interval 0.57 to 1.12.
Homologues: Orthologues: chimpanzee GNG3 (100% identical), dog GNG3 (100% identical), guinea pig GNG3 (100% identical), macaque GNG3 (100% identical), mouse Gng3 (100% identical), rabbit GNG3 (100% identical), rat Gng3 (100% identical), zebrafish gng3 (93% identical), tropical clawed frog gng3 (92% identical). Paralogues in human: GNG2 (72% identical), GNG4 (69% identical), GNG12 (57% identical), GNG7 (56% identical), GNG8 (52% identical), GNG10 (47% identical), GNG5 (44% identical), GNG5B (43% identical), GNGT2 (35% identical), GNG11 (33% identical), GNGT1 (33% identical).
Diseases named in the same sentence as GNG3 in open-access papers:
GNG3 is named in the same sentence as 10 diseases in open-access papers, as found by Europe PMC text mining. Sharing a sentence is not in itself a finding about the gene and the disease. The quoted sentences say what the papers report.
Obesity (3 papers, 2020 to 2021). Accumulation of substantial excess body fat. "Mice with deficiency of GNG3 are lean and have seizures, and also show resistance to opioids and diet induced obesity." (PMID 35310542, 2021).
glioblastoma (2 papers, 2019 to 2022). The most malignant astrocytic tumor (WHO grade IV).
cognitive decline (1 paper, 2025). "GNG3, a gamma subunit of G‐proteins, regulates synaptic transmission and has been linked to age‐related cognitive decline and behavioral deficits." (PMID 41047765, 2025).
epilepsy (1 paper, 2013). A brain disorder characterized by episodes of abnormally increased neuronal discharge resulting in transient episodes of sensory or motor neurological dysfunction, or psychic dysfunction. "The FS-DE network has three distinctive VIPs, CACNG2, KCNH3 and GNG3, with relevant roles in epilepsy." (PMID 24278214, 2013).
lung carcinoma (1 paper, 2020). "Inhibition of Cyclin K with siRNA significantly reduced basal expression levels of Cyclin D1 and GNG3, while increasing expression levels of PCDH9, WNT9A and GNG7 in two different lung cancer cell lines." (PMID 33042275, 2020).
lupus (1 paper, 2021). "Of note, two other main contributors to the lupus phenotype are also part of the PI3K-AKT pathway: Gm2436 (WIR = 19.88) and Gng3 (WIR = −30.02)." (PMID 33578738, 2021).
Stroke (1 paper, 2019). Sudden impairment of blood flow to a part of the brain due to occlusion or rupture of an artery to the brain. "We showed that the expression of Dlg4, Gria1, Grin2a, Gng3, Gnb5, MapK8, and Bdnf (encoding PSD-95, GluA1, GluNMDA2A, G-protein subunit gamma 3, G-protein subunit beta 5, JNK, and BDNF, respectively) was strongly reduced 1 week after stroke." (PMID 31888302, 2019).
tumor (1 paper, 2022). "Compared with normal tissues, tumor tissues had increased mRNA levels of GNG3 and PRXL2A and a reduced mRNA level of ITIH3." (PMID 35743699, 2022).
GNG3 also shares sentences with these, for which no sentence is quoted: Follicular Cyst (1 paper); nicotine addiction (1).